DIP2C (DIP2 acetate--CoA ligase C (putative))
Synonyms: KIAA0934
Tractability: PROTAC: ubiquitination databases record sites on it; its protein half-life has been measured.
Gene: Protein-coding gene on chromosome 10 (274,201 to 689,937, reverse strand). Ensembl gene ENSG00000151240.
Subcellular location (Human Protein Atlas): Nucleoplasm; Cytosol; Vesicles
Genetic constraint (gnomAD): Loss-of-function variants: 33 observed, 187.54 expected, observed/expected ratio (o/e) 0.18, 90% interval 0.13 to 0.23. The upper end of that interval is the gene's LOEUF score, 0.23, which puts it in group 1 of 6, group 1 being the genes least tolerant of losing a copy. Missense variants: 1,524 observed, 2,129.2 expected, observed/expected ratio (o/e) 0.72, 90% interval 0.69 to 0.75. Synonymous variants: 964 observed, 869.42 expected, observed/expected ratio (o/e) 1.11, 90% interval 1.05 to 1.17.
Homologues: Orthologues: mouse Dip2c (99% identical), rabbit DIP2C (99% identical), rat Dip2c (99% identical), pig DIP2C (98% identical), guinea pig DIP2C (97% identical), dog DIP2C (97% identical), macaque DIP2C (97% identical), chimpanzee DIP2C (96% identical), tropical clawed frog dip2c (96% identical), zebrafish dip2ca (91% identical), Drosophila melanogaster DIP2 (60% identical), Caenorhabditis elegans dip-2 (51% identical). Paralogues in human: DIP2A (75% identical), DIP2B (73% identical).
Diseases named in the same sentence as DIP2C in open-access papers:
DIP2C is named in the same sentence as 32 diseases in open-access papers, as found by Europe PMC text mining. Sharing a sentence is not in itself a finding about the gene and the disease. The quoted sentences say what the papers report.
breast carcinoma (4 papers, 2017 to 2025). "In support of this theory, DIP2C mutation was reported as a late event when the timing of mutations and chromosome rearrangements were investigated in a breast cancer genome." (PMID 28716088, 2017). "The DIP2C missense and frameshift mutations identified in breast cancer in previous studies are located predominantly in the first half of the transcript but outside the predicted DMAP1 binding domain." (PMID 28716088, 2017). "In lung cancer tissues and breast cancer cells, DIP2C was found to be significantly mutated." (PMID 39867879, 2024). "Further studies have estimated the DIP2C somatic mutation prevalence at ~5% of breast cancer cases." (PMID 28716088, 2017). "Mutations found in breast cancers are predicted to inactivate DIP2C function." (PMID 28716088, 2017). "Furthermore, high CD44 and low CD24 expression, characteristics associated with the breast cancer stem cell phenotype and the EMT state, was revealed in DIP2C KO cells, with potential implications for treatment and metastasis ability." (PMID 28716088, 2017). "Expression profiling revealed 780 genes for which the expression level was affected by the loss of DIP2C, including the tumour-suppressor encoding CDKN2A gene, the epithelial-mesenchymal transition (EMT) regulator-encoding ZEB1, and CD44 and CD24 that encode breast cancer stem cell markers." (PMID 28716088, 2017). "DIP2C expression was found to be decreased in the basal-like and HER-2 breast cancer subtypes." (PMID 32624706, 2020).
developmental delay (4 papers, 2018 to 2025). "The disco-interacting protein 2 homolog C (DIP2C) gene has been implicated in developmental delays." (PMID 37606455, 2023). "In another report, deletions including DIP2C and/or ZMYND11 were identified in several patients with developmental delay including three patients with seizures." (PMID 31190668, 2019).
lung carcinoma (3 papers, 2017 to 2024). "In this project significant phenotypic and transcriptional alterations were induced by loss of the candidate breast and lung cancer gene DIP2C in cancer cells." (PMID 28716088, 2017). "Mutations in DIP2C have been identified in lung cancer samples." (PMID 34809630, 2021). "The disco-interacting protein 2 homolog C (DIP2C) gene is an uncharacterized gene found mutated in a subset of breast and lung cancers." (PMID 28716088, 2017).
Anxiety (2 papers, 2023 to 2025). Intense feelings of nervousness, tension, or panic often arise in response to interpersonal stresses. "DIP2C may affect emotional regulation but lacks definitive connections to anxiety." (PMID 40125487, 2025). "Recent GWAS have also identified seven significant genetic loci—RNU6–168P, MAT2B, DKK2, DIP2C, COL22A1, OR4L1, and ATXN1—that influence anxiety traits in Caesarean-born offspring." (PMID 40125487, 2025).
autism (2 papers, 2023 to 2024). Persistent deficits in social interaction and communication and interaction as well as a markedly restricted repertoire of activity and interest as well as repetitive patterns of behavior. "NFIX has been predicted to target 28 autism risk genes, including DIP2C and CSNK1E." (PMID 39363111, 2024).
cervical carcinoma (2 papers, 2013 to 2017). A carcinoma arising from either the exocervical squamous epithelium or the endocervical glandular epithelium. "Notably, DIP2C is among seven genes on chromosome 10p14-15 whose loss has been associated with the ability to escape from senescence in cervical cancer." (PMID 28716088, 2017). "The effect of ectopic expression of SORBS2, TLR3, CYP4V2, FBXO18, IL15RA, WDR37 and DIP2C on the cell phenotype, in particular senescence, was investigated in primary cells, HPV-immortalized cells and cervical carcinoma cells." (PMID 24165198, 2013).
hyperglycaemia (2 papers, 2023). "According to the literature, DIP2c gene is very susceptible to be modified by external factors, so the hyperglycemia during pregnancy could be another modifier factor." (PMID 37415231, 2023).
Intellectual disability (2 papers, 2017 to 2018). "Furthermore this observation is interesting as decreased expression levels of both DIP2C and DIP2B are associated with mental retardation." (PMID 28716088, 2017).
acute myeloid leukemia (1 paper, 2016). Acute myeloid leukemia (AML) is a group of neoplasms arising from precursor cells committed to the myeloid cell-line differentiation. "Promoters with predominant interactions in this set of clusters include, for example, DIP2C (Disco-Interacting Protein 2 Homolog C) that shows high expression in acute myeloid leukemia." (PMID 27863249, 2016).
cerebral palsy (1 paper, 2019). A group of disorders affecting the development of movement and posture, often accompanied by disturbances of sensation, perception, cognition, and behavior. "De novo deletions of DIP2C have been reported in two patients with cerebral palsy, one of whom also had ADHD, and the other had seizures in infancy." (PMID 31190668, 2019).
colorectal cancer (1 paper, 2017). A primary or metastatic malignant neoplasm that affects the colon or rectum. "We then targeted the human colorectal cancer cell line RKO, also well known to function with rAAV technology, and obtained three heterozygous knock-out clones (DIP2C+/− #1-3) following screening of 605 Geneticin-resistant clones, indicating <1% targeting efficiency." (PMID 28716088, 2017).
endometriosis (1 paper, 2025). The growth of functional endometrial tissue in anatomic sites outside the uterine body. "The p-values indicate that four genes (DIP2C, DNMT1, RRP1, and USP1) are significantly differentially hypomethylated in the endometriosis group compared to the control group." (PMID 39858463, 2025).
major depressive disorder (1 paper, 2026). An episode of depression lasting two or more weeks without an intervening episode of mania. "LHCV-specific genes were involved in cellular signalling, and Mendelian randomisation (MR) analyses supported a potential causal association between brain expression of DIP2C and increased risk of major depressive disorder." (PMID 42114417, 2026).
Neurodevelopmental delay (1 paper, 2025). "10p15.3 microdeletion syndrome is a rare genetic disorder characterized by the loss of ZMYND11 and DIP2C genes, resulting in a range of neurodevelopmental delays, dysmorphic features, and gastrointestinal (GI) symptoms." (PMID 39958070, 2025).
pulmonary disease (1 paper, 2021). "This demonstrated that DIP2C gene indeed plays an important role at the pulmonary disease." (PMID 34809630, 2021).
Tourette syndrome (1 paper, 2023). A neurologic disorder caused by defective metabolism of the neurotransmitters in the brain. "Variants in DIP2C (disco interacting protein 2 homolog C) and DNAH17 (dynein axonemal heavy chain 17) have been previously linked to ASD, and WWC1 was identified as a risk gene for Tourette syndrome, another NDD known to be comorbid with ASD." (PMID 37686052, 2023).
Usher syndrome (1 paper, 2025). A syndromic diseae characterized by the association of sensorineural deafness (usually congenital) with retinitis pigmentosa and progressive vision loss. "According to our meta-analysis of transcriptomic data, IGHV1-69D and GAD1 are significantly upregulated, whereas WNT5A and DIP2C are significantly downregulated in Usher syndrome." (PMID 40723835, 2025). "IGHV1-69D and GAD1 demonstrated statistically significant upregulation in Usher syndrome samples compared to controls (p < 0.05), while WNT5A and DIP2C exhibited a significant downregulation (p < 0.05)." (PMID 40723835, 2025).
tumor (7 papers, 2013 to 2026). "The epithelial and mesenchymal states impact the stages of tumorigenesis differently, suggesting that timing may influence the effect of DIP2C mutations on tumour development." (PMID 28716088, 2017). "DIP2C is considered a potential tumor promotor, possibly involved in epigenetic regulation and DNA methylation." (PMID 41536518, 2026). "Through the HPA database, we found that three genes (ABCC9, AHNAK, and DIP2C) had low expression in patients with tumours, whereas eight genes (PLOD1, SLC3A2, RUNX2, RAD9A, CHMP4C, DARS2, CLIC3, and POU5F1) were highly expressed." (PMID 36685927, 2022). "Through the HPA database, we found that three genes, namely ABCC9, AHNAK, and DIP2C, had low expression in patients with tumours, and eight other genes—PLOD1, SLC3A2, RUNX2, RAD9A, CHMP4C, DARS2, CLIC3, and POU5F1—were highly expressed in patients with tumours." (PMID 36685927, 2022). "To understand the role of DIP2C in tumour development we studied the gene in human cancer cells." (PMID 28716088, 2017). "The disco-interacting protein 2 homolog C (DIP2C), an uncharacterised gene expressed at high level in most human solid tissues and adult tumour types, was identified by us as a putative cancer gene in exome-wide mutational analyses of hormone-receptor negative breast tumours." (PMID 28716088, 2017). "While three genes (AHNAK, ABCC9, and DIP2C) were highly expressed in normal tissues, eight genes (CHMP4C, CLIC3, DARS2, PLOD1, POU5F1, RAD9A, RUNX2, SLC3A2) were highly expressed in tumour tissues." (PMID 36685927, 2022). "Eight genes (SLC3A2, DARS2, DIP2C, PLOD1, RUNX2, ABCC9, AHNAK, and CLIC3) may be involved in the malignant transformation of tumours, and three genes (CHMP4C, POU5F1, and RAD9A) may have a protective effect in patients with tumours." (PMID 36685927, 2022). "We chose 4 genes (KIF25, E2F1, DIP2C, TFG) that were present in at least 4 tumor patients, were not present in the healthy population, were detected outside of patients 18, 19, 30, 34, and 38, and have the potential to serve as therapeutic targets or diagnostic and predisposing biomarkers." (PMID 38982214, 2024).
cancer (5 papers, 2017 to 2024). A tumor composed of atypical neoplastic, often pleomorphic cells that invade other tissues. "Loss of DIP2C can affect DNA methylation and changes in gene expression, cellular senescence, and epithelial-mesenchymal transition in cancer cells." (PMID 38982214, 2024). "Loss of DIP2C triggers substantial DNA methylation and gene expression changes, cellular senescence and epithelial-mesenchymal transition in cancer cells." (PMID 28716088, 2017). "The engineered isogenic cell system and the stable overexpression clones were then used to study the phenotypes associated with DIP2C expression in cancer cells." (PMID 28716088, 2017). "In summary, expression profiling revealed hundreds of genes, many of which implicated in processes linked to cancer, for which expression was altered by DIP2C knockout." (PMID 28716088, 2017). "Here we exploited rAAV-mediated gene targeting to knock out one or two alleles of DIP2C in human cancer cells, enabling DIP2C to be studied under control of its endogenous promoter." (PMID 28716088, 2017). "Thus far DIP2C is the only family member that has been identified as a candidate cancer gene through somatic mutation analysis." (PMID 28716088, 2017). "In a human cancer cell line, knockdown of DIP2C was found to induce extensive DNA methylation, gene expression variation, cell death, and epithelial–mesenchymal transition." (PMID 32624706, 2020). "We engineered human DIP2C knockout cells by genome editing in cancer cells." (PMID 28716088, 2017). "Genomic profiling has revealed a large subset of genes as likely drivers of breast tumorigenesis, including the hitherto non-characterized DIP2C gene which is interesting in association to cancer development since it may belong to the growing number of epigenetic regulators implicated in cancer." (PMID 28716088, 2017).
skeletal dysplasia (1 paper, 2021). Any Mendelian diseases that affects growth and development of the skeleton. "DIP2C has been shown to regulate DNA methylation and the epithelial–mesenchymal transition in human cell lines, and mutations in DIP2C have been associated with skeletal dysplasia affecting bone and cartilage development in humans." (PMID 34122511, 2021).
DIP2C also shares sentences with these, for which no sentence is quoted: neurodevelopmental disorder (2 papers); Alzheimer disease (1); atherosclerosis (1); deafness dystonia syndrome (1); genetic disorder (1); infection (1); Insulin resistance (1); melanoma (1); microcephaly (1); prostate carcinoma (1); spastic hemiplegia (1); speech disorder (1).